PPARG (peroxisome proliferator activated receptor gamma)
Diseases named in the same sentence as PPARG in open-access papers (continued):
Sharing a sentence is not in itself a finding about the gene and the disease.
breast cancer (continued). "In breast cancer, PPARγ promotes terminal differentiation of malignant breast epithelial cells, and its activation triggered by drugs like antidiabetic thiazolidinedione (TZD) is associated with reduced cell growth and less malignancy." (PMID 28212608, 2017). "Further, polymorphisms in VDR have been demonstrated to be associated with breast cancer risk and both RXR and PPARγ have been demonstrated to comprise anti-cancer cell activity." (PMID 28427429, 2017). "VDR, RXR and PPARγ were even detected in those cancers characterized as both triple negative and highly proliferative - two basic features of basal like breast cancer." (PMID 28427429, 2017). "This study analyzed VDR, RXR and PPARγ by immunohistochemistry in BRCA1 associated (n = 38) and sporadic breast cancer (n = 79)." (PMID 28427429, 2017). "We also detected co-immunoprecipitation of endogenous PNR and PPARγ proteins in the breast cancer cell line MDA-MB-468." (PMID 28300834, 2017). "Psammaplin A also activates the peroxisome proliferator-activated receptor γ (PPARγ) and induces apoptosis in human breast cancer cells." (PMID 29220359, 2017). "15d-PGJ2 induces apoptosis PPARγ-dependently in neuroblastoma and hepatic myofibroblasts, whereas PPARγ-independently in colorectal cancer, breast cancer, hepatocellular carcinoma and prostate and bladder carcinoma." (PMID 28955990, 2017). "In the present study, we observed that BRL at 10 μM of concentration for 24 h did not decrease cell viability but it was able to inhibit, in a PPARγ-dependent manner, migration and invasion of breast cancer cells." (PMID 27556298, 2016). "This genetic rescue further supports that Gpr132 is an essential mediator of macrophage PPARγ regulation of breast cancer progression." (PMID 27692066, 2016). "Here we report that macrophage PPARγ deletion in mice not only exacerbates mammary tumor development but also impairs the anti-tumor effects of rosiglitazone." (PMID 27692066, 2016). "Single treatment with γ-T3, PPARγ agonists (rosiglitazone or troglitazone) or antagonists (GW9662 or T0070907) resulted in a dose-dependent growth inhibition of breast cancer cells." (PMID 27669218, 2016). "Malaviya and Sylvester examined the anti-proliferative effect of γ-T3 in combination with PPARγ agonists or antagonists on breast cancer cells (MCF-7 and MDA-MB-231)." (PMID 27669218, 2016). "Here, we have identified, for the first time, a functional PPAR responsive element within the CXCR4 promoter that is responsible of the PPARγ-mediated inhibition of CXCR4 expression in breast cancer cells." (PMID 27556298, 2016). "In conclusion, our data highlight a novel role for PPARγ in controlling breast cancer progression and in affecting CAF behavior." (PMID 27556298, 2016). "Overall, these findings clearly demonstrated that ligand-activated PPARγ by binding to a newly identified PPRE motif within the CXCR4 promoter downregulates CXCR4 expression levels in human breast cancer cells." (PMID 27556298, 2016). "Given the largely documented role of SDF-1α/CXCR4 axis in modulating cancer cell migration, we next assessed the ability of PPARγ agonist to influence cell migration and invasion of both breast cancer cells." (PMID 27556298, 2016). "To determine the effects of macrophage PPARγ deletion on breast cancer progression, we performed mammary fat pad orthotopic injections of C57BL/6J-compatible mouse breast cancer cells EO771 in female mice, and followed tumor growth by measuring tumor size." (PMID 27692066, 2016). "We have then shown the ability of ligand-activated PPARγ to counteract stroma-induced breast cancer cell migration and invasiveness." (PMID 27556298, 2016).
breast cancer (continued). "In contrast, between DMBA + ROSI-treated strains, PPARγ-MG KO mice had a ~2-fold higher mammary tumour incidence compared to PPARγ-WTs (53 ± 12 vs. 29 ± 8%, respectively), although this trend was not statistically significant." (PMID 25889730, 2015). "Morusin has the potential to inhibit human breast cancer cell growth in vitro and in vivo through C/EBPβ and PPARγ mediated lipoapoptosis." (PMID 26538209, 2015). "TZD18, a PPARγ/δ dual ligand, activated ER stress response and induced growth arrest and apoptosis in breast cancer cells." (PMID 26061913, 2015). "Variable PPARγ protein levels were observed among mammary tumours from PPARγ-WT and PPARγ-MG KO by Western blot analysis." (PMID 25889730, 2015). "Despite the fact that samples of aggressive tumors showed increased PPARγ expression, TZDs displayed moderate positive effects in breast cancer models." (PMID 25866814, 2015). "Twenty-five percent of DMBA Only-treated PPARγ-MG KO mice developed palpable mammary tumours by week 25, and this significantly declined to week 16 in DMBA + ROSI-treated PPARγ-MG KOs (p < 0.01)." (PMID 25889730, 2015). "The PTEN gene promoter also reportedly contains a PPRE, and so it was not surprising that PTEN protein levels were markedly reduced among PPARγ-MG KO mammary tumours in the DMBA Only group." (PMID 25889730, 2015). "Similar to our results, cytoskeletal organization is altered in 15d-PGJ2 stimulated breast cancer cells (MCF-7) mediated through a mechanism unrelated to PPARγ transcriptional activation." (PMID 26457076, 2015). "Given recent evidence implicating a protective role for PPARγ in breast cancer, the MG cell-specific contribution of this receptor was evaluated during DMBA-induced breast tumourigenesis using PPARγ-MG KO and PPARγ-WT mice." (PMID 25889730, 2015). "In DMBA + ROSI-treated mice, mammary tumours isolated from PPARγ-WT mice were primarily identified as squamous cell carcinomas; whereas, those from PPARγ-MG KO mice were classified as more malignant lesions that ranged from well-to-moderately differentiated." (PMID 25889730, 2015). "In DMBA Only-treated mice, mammary tumour incidences were modestly higher among PPARγ-WTs (32 ± 9%) compared to PPARγ-MG KOs (26 ± 7%)." (PMID 25889730, 2015). "DMBA Only-treated PPARγ-MG KO mice had a significant ~5-fold decrease in mean mammary tumour volume compared to similarly treated PPARγ-WTs (mean log volume: 360.6 mm3 vs. 1843 mm3, respectively; p < 0.05)." (PMID 25889730, 2015). "Further, DMBA + ROSI-treated PPARγ-MG KO mice exhibited a ~2-fold higher incidence of mammary tumours compared to DMBA Only-treated PPARγ-MG KOs (53 ± 12% vs. 26 ± 7%, respectively) in a trend that approached statistical significance (p = 0.07)." (PMID 25889730, 2015). "Cotreatment with DMBA + ROSI abolished this genotypic difference, and resulted in similar mean mammary tumour volumes via increases in PPARγ-WTs (806.9 mm3) and decreases in PPARγ-MG KOs (818.0 mm3)." (PMID 25889730, 2015). "Among PPARγ-WT mice, palpable mammary tumours were first observed following DMBA treatment at week 11, and at week 13 in the DMBA + ROSI-treated group." (PMID 25889730, 2015). "Other groups have examined the MG-specific contribution of PPARγ in breast cancer, using overexpression and dominant negative knockout approaches that only target the PPARγ1 isoform." (PMID 25889730, 2015). "On the other hand, these events seem to be avoided in HER2-overexpressing breast carcinoma cells, through the conversion and storage of FAs as triglycerides by peroxisome proliferator-activated receptor gamma (PPARγ)." (PMID 26640797, 2015). "It is of great importance to further investigate if lipogenesis regulated by acetylation of the Pparγ lysine motif (K154/155) contributes to the progression of ErbB2-positive breast cancer." (PMID 25229978, 2014).
breast cancer (continued). "The survival of breast cancer cells, especially those with ErbB2/Her2 overexpression, is highly dependent upon the lipid metabolism induced by Pparγ, which protects cells from palmitate toxicity." (PMID 25229978, 2014). "In the current study, we investigated the role of Pparγ K154/155 acetylation on lipid production in ErbB2-positive breast cancer cells." (PMID 25229978, 2014). "Our studies thus provide evidence for the usefulness of PTER-ITC in breast cancer therapy involving various pathways, including PPARγ." (PMID 25119466, 2014). "Collectively, our observations suggest potential applications for PTER-ITC in breast cancer prevention and treatment through modulation of the PPARγ activation pathway." (PMID 25119466, 2014). "Our results showed that when pre-treated with PPARγ antagonists or PPARγ siRNA, both breast cancer cell lines suppressed PTER-ITC-induced apoptosis, as determined by annexin V/propidium iodide staining and cleaved caspase-9 expression." (PMID 25119466, 2014). "To establish the essential role of PTER-ITC in PPARγ-mediated apoptosis of breast cancer cells, we used PPARγ siRNA and its drug antagonist to inhibit PPARγ signaling, and demonstrated apoptosis prevention and caspase activation." (PMID 25119466, 2014). "This work provides a novel mechanism through which Pparγ regulates lipid metabolism via conserved acetylation sites in breast cancer cells." (PMID 25229978, 2014). "miR-27b directly targets peroxisome proliferator-activated receptors γ (PPARγ), and functions as an oncogene in breast cancer in a cell-type dependent style." (PMID 24945253, 2014). "We have previously shown that active Pparγ promotes ErbB2-positive breast cancer growth through enhanced angiogenesis." (PMID 25229978, 2014). "In this report, we have shown that the conserved acetylation site (K154/155) of Pparγ plays a critical role in breast cancer cell lipid synthesis." (PMID 25229978, 2014). "The majority of previous studies have supported that PPARγ is a factor of good prognosis for breast cancer." (PMID 24944709, 2014). "This treatment was also shown to result in decreased expression of PPARγ and RXR, and these effects were associated with a significant decrease in breast cancer cell growth." (PMID 23431460, 2013). "In this study, we aim to study the relationship between expression of cytoplasmic PPARγ and Skp2 expression in breast cancer, and investigate the mechanisms by which Skp2 regulates cytoplasmic localization of PPARγ." (PMID 23939428, 2013). "Particularly, the downregulation of ERα expression is noteworthy since ERα has been shown to bind to PPRE and negatively interfere with PPARγ signaling in breast cancer cells." (PMID 23843889, 2013). "Results from these studies further characterize the anticancer mechanism of action of γ-tocotrienol, as well as PPARγ agonist and antagonists, and provides insights as to potential benefits of these therapies in the treatment of breast cancer." (PMID 23431460, 2013). "The present study also confirms and extends previous findings showing that treatment with PPARγ antagonists significantly inhibits growth of breast cancer cells." (PMID 23431460, 2013). "This hypothesis is further evidence by the finding that PPARγ expression is elevated in breast cancer cells as compared to normal mammary epithelial cells, and mice genetically predisposed to developing mammary tumors constitutively express high levels of activated PPARγ as compared to control mice." (PMID 23431460, 2013). "To explore the significance of PPARγ in human breast cancer progression, we examined the subcellular distribution of endogenous PPARγ in human breast cancer cells." (PMID 23939428, 2013). "Several lines of evidence indicate that PPARγ plays a pivotal role in mediating DMC's antiproliferative activity in breast cancer cells." (PMID 23843889, 2013).
breast cancer (continued). "The expression of cytoplasmic PPARγ was reduced in estrogen receptor positive (ER-positive) human breast cancer (well differentiated) correlating with weak Skp2 abundance." (PMID 23939428, 2013). "The typical case showed that the high expression of cytoplasmic PPARγ was correlated with high Skp2 expression in the same breast cancer specimen (ER-negative, PR-negative, stage III)." (PMID 23939428, 2013). "Our data demonstrate the importance of exploring the role of nuclear receptors (PPARα/PPARγ) in the regulation of pro-inflammatory pathways, with the aim to thwart breast cancer stem cells functioning." (PMID 23372804, 2013). "In this study, the role of cytoplasmic PPARγ and Skp2 expression was investigated in human breast cancer progression." (PMID 23939428, 2013). "In this report, we studied the clinical significance and relationship between cytoplasmic localization of PPARγ and Skp2 expression in human breast cancer." (PMID 23939428, 2013). "We demonstrated for the first time that Skp2 overexpression provokes cytoplasmic localization of PPARγ upon MEK1-dependent mechanisms in human breast cancer cells." (PMID 23939428, 2013). "We obtained first evidence that DMC induced apoptotic death in breast cancer cells, at least in part, through a PPARγ-dependent mechanism." (PMID 23843889, 2013). "Higher dose ranges of γ-tocotrienol in combination with these same doses of PPARγ antagonists resulted in a complete suppression in breast cancer cell growth such that viable cell number was undetectable using the MTT assay (data not shown)." (PMID 23431460, 2013). "PPARγ has been found in cells from various lineages, e.g., colon cancer, stomach cancer, breast cancer, and prostate cancer." (PMID 23516550, 2013). "Third, DMC induced autophagy through mTOR inhibition, which is reminiscent with that reported with TZD PPARγ agonists in breast cancer cells." (PMID 23843889, 2013). "Ligand activated PPARγ is reported to inhibit invasion and metastasis of breast cancer cells and induce G1/S arrest by upregulation of p21WAF1/Cip1or p27Kip1, and downregulation of cyclin D1." (PMID 23431283, 2013). "Using immunohistochemistry, we examined the clinical significance of cytoplasmic PPARγ and Skp2 in paraffin-embedded mammary tissue sections screened from twenty benign breast diseases and fifty breast cancer patients." (PMID 23939428, 2013). "The low level of PPARγ expression observed in breast cancer tissue has been suggested to be a possible therapeutic target for the prevention of breast cancer progression." (PMID 24137293, 2013). "Our results emphasize the importance of the cytoplasmic localization of PPARγ in the development and progression of breast cancer." (PMID 23939428, 2013). "Our data revealed that expression of cytoplasmic PPARγ was positively related with Skp2 expression, which is critical to the development and progression of breast cancer." (PMID 23939428, 2013). "We found that PPARγ in the benign breast disease showed positive immunoreactivity mostly in the nucleus, while ER-negative breast carcinoma samples (poorly differentiated) displayed cytoplasmic mainly staining." (PMID 23939428, 2013). "Expression of cytoplasmic PPARγ was increased in poorly differentiated breast carcinoma samples, which was similar to the reports of other research groups." (PMID 23939428, 2013). "A more recent work, finally, suggests for PPARγ a dual role as a tumor-promoting factor in neuroblastoma cells and as a tumorsuppressor in breast cancer cells." (PMID 22848209, 2012). "Of the three subtypes, PPARγ is the major species expressed in the mammary gland and in primary and metastatic breast cancer and breast cancer cell lines." (PMID 22538444, 2012). "Another study has showed that HER2-overexpressing breast cancer cells present an increased PPARγ expression that exacerbates tumor development as it fuels lipogenic enzymes reducing accumulated fatty acids toxicity." (PMID 22848209, 2012).
breast cancer (continued). "Although many studies have addressed the interactions between different nuclear receptor subfamilies, an area of relevance to breast cancer is the inhibitory effect of PPARγ on ERα (ER) promoter activation through its interaction with ER response elements." (PMID 22538444, 2012). "ESA has been shown to suppress tumor angiogenesis and MCF-7 breast cancer cell proliferation via PPARγ activation, induce apoptosis via lipid peroxidation, and induce autophagy-dependent cell death through AKT/mTOR and ERK1/2 signal targeting." (PMID 21904603, 2011). "It concludes that PPARγ triggers apoptotic events in breast cancer cells via Fas/FasL signaling pathway." (PMID 22135675, 2011). "Particularly in breast cancer, stimulation of PPARγ increases the degradation of cell cycle genes (Cyclin D1), interferes with estrogen receptor signaling, and NF-κB signaling cascades." (PMID 22254089, 2011). "In MCF-7 and T47D breast cancer cells, γ-TmT, γ-tocopherol, and more strongly δ-tocopherol enhance the transactivation of PPARγ." (PMID 22254089, 2011). "Antitumor activity of PPARγ agonists has been shown in tumor cells derived from liposarcoma, colon cancer, breast cancer, leukemia, gastric cancer, nonsmall cell lung cancer, and prostate cancer." (PMID 20182546, 2010). "In the same direction, the present study showed evidence of down-regulation of PPARG in breast cancer tissue." (PMID 21059268, 2010). "We previously demonstrated that human breast cancer cell lines expressed PPARα and PPARγ, and their lipid ligands inhibited proliferation of these cells." (PMID 21080969, 2010). "PPARγ has shown promise in therapy promoting terminal differentiation and apoptosis in a variety of malignancies, including liposarcoma, breast cancer, leukemia, gastric cancer, non‐small cell lung cancer, and prostate cancer." (PMID 20182546, 2010). "Subsequent hierarchical clustering suggested that a number of those genes (including PPARG, FGF2, APOB, CRHBP, CETP, and RXRG) were significantly associated with breast cancer that appeared repeatedly in different GO-terms." (PMID 21059268, 2010). "PPARγ has previously been linked with the PTEN pathway, it transactivates the PTEN promoter, and PPARγ agonists increase PTEN expression in breast cancer cell lines." (PMID 20712882, 2010). "C-DIMs activate PPARγ in a number of cancer cell types including ovarian, bladder, colon, pancreatic and ER-negative and ER-positive breast cancer cells." (PMID 21129193, 2010). "To determine if PPARγ regulates telomerase activity in breast cancer, we examined the effect of the PPARγ ligand, troglitazone, on telomerase activity in breast cancer cell lines." (PMID 20650001, 2010). "To examine potential synergistic effects of synthetic PPAR and RXR ligands on these lines, we treated human breast cancer cells with the PPARα agonist clofibrate, the PPARγ selective ligand ciglitazone, and the RXR selective agonist AGN194204." (PMID 21080969, 2010). "It has been suggested that PPARγ is a tumor suppressor gene in a variety of malignancies including breast cancer." (PMID 20650001, 2010). "PPARγ enables ERBB2-positive breast cancer cells to convert fatty acids to triglycerides in order to avert lipotoxicity caused by the significantly high levels of fats that these cells produce." (PMID 19298655, 2009). "We sought to examine the reasons for the dependence of ERBB2-positive breast cancer cells on PPARγ for survival." (PMID 19298655, 2009). "We have previously observed interaction between PPARγ Pro12Ala and NSAID use in relation to risk of both breast cancer and lung cancer using the Diet, Cancer and Health cohort and the same definitions of NSAIDs as used here." (PMID 19500413, 2009). "In this study, we provide evidence that rosiglitazone significantly increases the level of PPARγ in mammary tumours, leading to significant reduction in tumour volume." (PMID 19356226, 2009).